INS (insulin)
Diseases named in the same sentence as INS in open-access papers (continued):
Sharing a sentence is not in itself a finding about the gene and the disease.
Insulin resistance (continued). "Therefore, we aimed to investigate the potential association between green coffee extract (GCE) and fasting blood glucose (FBG), insulin and homeostatic model assessment of insulin resistance (HOMA-IR) by pooling together the results from clinical trials." (PMID 31709016, 2019). "A random effects model was used to estimate overall Fisher’s Z and 95% confidence interval of glycemic parameters including fasting plasma glucose (FBG), serum fasting insulin level, homeostasis model assessment-estimated insulin resistance (HOMA-IR) and glycated hemoglobin (HbA1c)." (PMID 31289463, 2019). "Therefore, the phosphorylation of IRS-1 at ser307 is considered to be a major player in insulin signaling and insulin resistance." (PMID 30871060, 2019). "Taken all together, daily oral administration of sitagliptin in group 3 maintained body weight, decreased serum glucose and insulin resistance with concomitant enhancement of insulin secretion, decreased total cholesterol and TGs, and increased islet number and islet size." (PMID 31881657, 2019). "In this study, we hypothesized that the insulin resistance or increased insulin levels in obesity might play a significant role in obesity-induced airway hyperresponsiveness and lung fibrosis via the TGF-β1 pathway." (PMID 31133649, 2019). "Therefore, CA can relieve hyperglycemia, insulin resistance and other symptoms of type 2 diabetes by promoting insulin power." (PMID 30867526, 2019). "Furthermore, in type 2 diabetes patients, insulin resistance is observed in the liver, muscle, and adipose tissue, which are the classical insulin target organs." (PMID 31357734, 2019). "In addition, JNKs seem to play a significant role in peripheral insulin resistance via cytokine production, inflammation and disruption of insulin signaling." (PMID 31270248, 2019). "Insulin-mediated microvascular recruitment depends on normal endothelial response to insulin and endothelial dysfunction negatively impacts insulin’s microvascular action thereby contributing to the development of vascular insulin resistance." (PMID 30699907, 2019). "This approach may gradually help avoid chronic hyperglycemia, reduce insulin resistance and consequently stabilize the insulin production of pancreatic beta-cell." (PMID 30700006, 2019). "In obese animals, hypothalamic insulin resistance might be also a consequence of impaired hypothalamic insulin signaling." (PMID 30906281, 2019). "Furthermore, intracellular accumulation of FFAs contributes to the development of insulin resistance by inducing posttranslational modifications of several components of the insulin signalling cascade." (PMID 31440740, 2019). "In addition to insulin resistance, another significant pathogenesis of DM is the failure to produce β-cell insulin in the pancreas, particularly in Type 1 DM." (PMID 31847392, 2019). "Small animal models of maternal obesity have provided robust evidence to suggest that metabolic disease can be programmed by adverse maternal nutrition during early-life, including abnormal glucose homeostasis and insulin signalling in offspring, insulin resistance, and obesity." (PMID 31300679, 2019). "Therefore, based on our findings presented here, we propose that visfatin exerts insulin-mimetic effects and thus enhances glucose uptake, improving insulin resistance." (PMID 31771561, 2019). "Furthermore, insulin resistance improved as evidenced by the decrease in fasting glucose (p < 0.05) and insulin concentrations (p < 0.001), together with a decrease (p < 0.001) in the HOMA as well as an increase (p < 0.001) in the QUICKI indices." (PMID 31484347, 2019). "In our study, we did not detect an association between visfatin and FPG, 2-h PG, insulin, 2-h insulin, or insulin resistance index." (PMID 31771561, 2019).
Insulin resistance (continued). "Overexpression of SIRT1 and many SIRT1 activators have beneficial effects on glucose homeostasis and insulin sensitivity in diabetic animal models and humans and down-regulation of SIRT-1 in several cells and tissues have been shown to cause insulin resistance." (PMID 31579450, 2019). "T2DM is the consequence of insulin resistance or insufficient insulin secretion." (PMID 31805752, 2019). "Cord blood insulin levels have not been described in association with insulin resistance in later life yet, and these two parameters are therefore not interchangeable." (PMID 31031804, 2019). "Indeed, an impairment in insulin signaling and the development of insulin resistance, which frequently proceed cardiac dysfunction in heart failure, are major determinant factors of HF progression." (PMID 31330848, 2019). "In addition, PGN can cause acute systemic insulin resistance by activating NOD1, and NOD1-deficient mice have reduced bacterial translocation to metabolic tissues and improved insulin tolerance." (PMID 31582899, 2019). "However, it cannot be ruled out that some of the children already suffered from early stages of insulin resistance, as mean fasting insulin levels and HOMA-IR were both already above those of children without metabolic abnormalities." (PMID 30889844, 2019). "Younger individuals required a higher mean insulin dose (U/kg) compared with older individuals throughout the trial, which may have been related to greater insulin resistance, in line with the tendency of a higher body mass index among younger individuals." (PMID 30891886, 2019). "However, when insulin secretory function is insufficient to counterbalance increasing insulin resistance, which correspond to the β-cell failure, hyperglycemia and T2D appears." (PMID 30678043, 2019). "Consequently, insulin resistance (IR) induced by this diet reduced insulin sensitivity from effectively metabolizing glucose in the untreated groups." (PMID 31739532, 2019). "Further, physical activity may enhance insulin sensitivity by reducing adipose tissue, which could block the vicious cycle of obesity-driven insulin resistance, decrease inflammatory cytokines, and increase adiponectin release from adipose tissues." (PMID 30822340, 2019). "In addition, an acute TNF-α infusion in healthy humans leads to insulin resistance through impaired insulin signaling and decreased glucose uptake." (PMID 30863203, 2019). "However, the increase of NEU1 activity in insulin target tissues reversed insulin resistance and glucose intolerance." (PMID 31521172, 2019). "Furthermore, the associations between the Nur77 and NOR1 protein response to insulin, with multiple measures of metabolic function, provides additional incentive to investigate Nur77 and NOR1 in the context of insulin resistance and T2DM." (PMID 30912283, 2019). "Furthermore, AD patients exhibit insulin resistance and decreased insulin signaling response in the hippocampus." (PMID 31160730, 2019). "Based on their findings, they concluded that age-related reductions in insulin-stimulated glucose oxidation contribute to the insulin resistance associated with aging, independent of the defect of glucose uptake." (PMID 31684154, 2019). "TNFα is secreted by adipocytes and macrophages and reduces insulin transduction which could result in glucose metabolic disorders, insulin resistance and obesity possibly followed by the later stadium type 2 diabetes." (PMID 31849810, 2019). "Interestingly, HMGB1 is also involved in DM initiation, altering insulin secretion and insulin resistance." (PMID 31835864, 2019). "Insulin resistance was mainly represented by insulin (loading = 0.70, p < 0.001)." (PMID 31801522, 2019). "We also observed increased plasma levels of IL10, which has been shown to inhibit the effects of IL6 with regards to insulin resistance, and may have contributed to the improved insulin sensitivity." (PMID 31724300, 2019).
Insulin resistance (continued). "In addition, the blood sugar level is elevated, and the surrogate parameters for insulin resistance and ß-cell function indicate insulin resistance with compensatory insulin secretion." (PMID 31709254, 2019). "Although the precise pathology of GDM remains unclear, it was reported to be related to increased insulin resistance and/or decreased insulin sensitivity during pregnancy." (PMID 31098383, 2019). "Ablation of Nr1i2 in the whole-body could protect mice from hyperglycemia and insulin resistance and showed improvement of metabolic functions and insulin sensitivity in T2D." (PMID 31579613, 2019). "Metformin may reverse insulin resistance, improve insulin signaling and correct lipid dysmetabolism." (PMID 30705766, 2019). "Insulin resistance is a complex metabolic abnormality that affects the ability of peripheral tissues to respond to insulin, leading to impaired peripheral tissue glucose utilization and resulting in the development of compensatory hyperinsulinemia and eventually hyperglycemia." (PMID 30699907, 2019). "As excessive fat accumulation in adipose tissue contributes to insulin resistance, and obesity is accompanied by hyperinsulinemia, the anti-adiposity effect of HON may be partly associated with an improvement in insulin signaling and hyperinsulinemia." (PMID 31075962, 2019). "Our Mendelian Randomization study suggests a positive association of insulin and insulin resistance with MI overall and in men, and with angina in men but not women, with validation for MI overall in CARDIoGRAPMplusC4D 1000 Genomes." (PMID 31508506, 2019). "Given the definite role of free fatty acids on mitochondrial dysfunction and hepatic insulin resistance, this review aims to explore the complex relationship among hepatic fatty acid accumulation, mitochondrial dysfunction, hepatic insulin resistance, and mitophagy." (PMID 31649547, 2019). "Cluster 4, expressed at high levels in dorsolateral prefrontal cortex, is enriched in genes involved in insulin synthesis; obesity and insulin resistance are closely related to the functions of the hippocampus, angular gyrus, and dorsolateral prefrontal cortex." (PMID 31428131, 2019). "Insulin resistance and inadequate insulin secretion remain the core defects in T2DM." (PMID 30941040, 2019). "A first study showed in C2C12 myotubes that palmitate-induced insulin resistance implied an increase in ceramide concentrations via their de novo biosynthesis pathway, leading to the inhibition of Akt, a crucial kinase from the insulin signaling pathway." (PMID 30678043, 2019). "On the other hand, lean women who tend to have low insulin resistance and normal fasting insulin levels may be more likely to be affected by the increase in estrogens that results from the intake of alcohol." (PMID 31284691, 2019). "However, in cases of women who have either more insulin resistance or impaired insulin secretion at pregnancy, gestational diabetes mellitus (GDM) then develops." (PMID 31275653, 2019). "Chronic INI in 3×Tg-HFD + INI mice was able to reduce the excess in brain GU seen in 3×Tg-HFD mice, and re-establish a normal acute response to insulin at 8 months of age, although cerebral insulin resistance was present at 14 months, consistent with raising blood glucose levels." (PMID 31130848, 2019). "Impairments in insulin signaling leads to insulin resistance, and type 2 diabetes mellitus (T2DM)." (PMID 30871083, 2019). "Insulin resistance (IR) is a pathological condition in which target tissues (primarily skeletal muscle, liver, and adipose tissue) have an impaired biological response to insulin stimulation." (PMID 31258478, 2019). "Both insulin secretion defect and insulin resistance are major mechanisms of T2DM." (PMID 31772943, 2019). "However, injection of FGF-1 similarly reduced HFD-induced glucose and insulin levels and improved insulin resistance under fasting conditions, which eliminated the effect of individual body weight on insulin sensitivity." (PMID 31866871, 2019).
Insulin resistance (continued). "Plasma IGFBP-2 levels correlate with insulin resistance and could be used as a biomarker of insulin sensitivity and may play an important role in the pathogenesis of obesity complications in early life." (PMID 30392760, 2019). "Increased Akt/mTOR signaling may contribute to the progression of steatosis in case of higher insulin levels in insulin resistance by inhibiting autophagy." (PMID 31509973, 2019). "In addition, we found that licochalcone A can improve fasting blood glucose, and blood insulin values, ameliorating insulin resistance in obese mice." (PMID 31083505, 2019). "Treatment with BMLE yielded significant improvements in insulin resistance and insulin sensitivity." (PMID 30841887, 2019). "Besides, we also observed a potential role for galectin-3 in hepatocyte, adipocyte, and myocyte insulin resistance, suggesting that galectin-3 can link inflammation to decreased insulin sensitivity." (PMID 31080833, 2019). "Hyperinsulinemic-euglycemic clamp studies also showed systemic insulin resistance, enhanced gluconeogenesis, accompanied by impaired insulin signaling and elevated gluconeogenic gene expression in the liver, although the impairment was not evident in skeletal muscle." (PMID 30814508, 2019). "This study is the first step toward uncovering the role of different SNAREs in insulin stimulated cardiac GLUT4 trafficking and is of clinical relevance due to the association of cardiac insulin resistance with diabetic cardiomyopathy and myocardial infarction." (PMID 31920989, 2019). "Women with NAFLD had higher BMI, WC, FBG, insulin and insulin resistance, as measured by HOMA-IR." (PMID 31770380, 2019). "High concentrations of insulin (250 nM) induced chronic insulin resistance in cells." (PMID 31635074, 2019). "Taken together, we can draw a conclusion that JNK may be a center of the pathobiology of insulin resistance in liver, and may affect insulin signalling through Cdc42-MKK4 pathway." (PMID 30621321, 2019). "Although the pathogenesis of GDM remains unclear, it is considered as a complex disease caused by multiple factors including genetic, environment, lifestyle, and other random factors that related to reduction of insulin sensitivity and insulin resistance." (PMID 31098383, 2019). "In some studies, chronic treatment with rapamycin caused insulin resistance or glucose intolerance without insulin resistance, but also insulin sensitization with glucose intolerance." (PMID 31406105, 2019). "However, at the same time, inhibition of insulin-AKT signaling can also precipitate metabolic insulin resistance." (PMID 31754457, 2019). "Insulin resistance, a condition established by genetic and environmental factors, leads to impaired glucose tolerance due to an imbalance between insulin sensitivity and insulin secretion." (PMID 31340611, 2019). "Moreover, they also found a significant reduction of the homeostatic model assessment of insulin resistance (HOMA-IR) and the adipose tissue insulin resistance (Adipo-IR) scores in comparison to non OA–treated insulin-resistant rats." (PMID 31450844, 2019). "In the case of obesity, adipose tissue produces proinflammatory cytokines such as TNF-α, IL-6 leptin, visfatin and angiotensin II, which modulate insulin resistance in two ways: directly, by signaling through the insulin pathway, and indirectly, by stimulating the inflammatory pathways." (PMID 31998288, 2019). "Furthermore, qRT-PCR results indicated that VT influenced the expression of Irs1, Akt2, Mtor genes in the Akt signaling pathway, suggesting that VT enhanced insulin signaling and improved liver insulin resistance." (PMID 31096578, 2019). "In a previous study on insulin resistance in patients with heart failure, fasting blood glucose levels were similar in controls and chronic heart failure patients, but heart failure patients had higher plasma insulin levels." (PMID 31461405, 2019).
Insulin resistance (continued). "Nonetheless, independently on whether mitochondrial dysfunction represents a primary defect in the pathogenesis of insulin resistance, increasing mitochondrial function represents a promising approach to enhance insulin sensitivity." (PMID 31130874, 2019). "Insulin resistance and insufficiency of insulin secretion are the basis of type 2 diabetes." (PMID 31212585, 2019). "Furthermore, in both obesity and T2DM, the levels of plasma free fatty acids (FFA) are elevated, which is conducive to insulin resistance and impaired insulin secretion." (PMID 31372175, 2019). "At baseline, ATX levels were positively associated with body mass index, fat mass, insulin resistance (HOMA‐IR) as well as insulin and leptin levels and negatively with fat‐free mass." (PMID 30821134, 2019). "Prediabetes and T2D are often associated with insulin resistance, where individuals produce insulin but are hyperglycaemic because their cells do not respond to insulin." (PMID 31142858, 2019). "Consistently, calculation of HOMA-IR (ESM), HOMA-B (ESM), QUICKI (ESM) and measurement of phosphorylated IRS-1 in liver lysates, showed that animals treated with STZ, either alone or in combination with CFTRinh172, displayed evidence of insulin resistance and poor insulin sensitivity." (PMID 31375720, 2019). "Therefore, the aim of the present study was to evaluate the relationships of serum fetuin-B concentration with indices of insulin resistance and insulin secretion, and with markers of liver steatosis in PCOS women in comparison to the control group." (PMID 31307012, 2019). "This tissue-specific protection from insulin resistance in adipose tissue may have an important role in the development of obesity because it allows insulin to increase glucose uptake and synthesize triglycerides in this tissue." (PMID 30832230, 2019). "Furthermore, the insulin tolerance test demonstrated that Adipo-Zfp238 KO mice had significant insulin resistance." (PMID 30677742, 2019). "Negative genetic associations were observed with several “unfavorable” metabolic phenotypes (such as fasting insulin, fasting glucose or insulin resistance), suggesting that metabolic factors might be involved in dysregulation of weight and appetite in AN." (PMID 30519816, 2019). "As a result, any defects or abnormalities of the insulin related signaling pathways may result in insulin resistance." (PMID 31071176, 2019). "Moreover, NGF is able to stimulate the insulin pathway in control conditions and to improve insulin resistance induced by chronic high insulin in cultured cholinergic neurons." (PMID 29736736, 2019). "Some patients presenting insulin resistance need more supplemental insulin." (PMID 31828166, 2019). "Moreover, the serum sclerostin levels exhibit a positive correlation with fasting glucose and result in insulin resistance; but negatively correlated with whole-body glucose disposal and insulin clearance rate." (PMID 31736870, 2019). "On the other hand, several studies demonstrate that metabolites such as ceramides may play a central role in mediating FA-induced insulin resistance, by acting at different levels of insulin signaling." (PMID 31010049, 2019). "Patients with hyperglycemia may develop insulin resistance, and an increase in insulin levels may induce cell proliferation." (PMID 31799199, 2019). "Mice fed with HFD displayed insulin resistance and had a blunted response to the exogenous insulin." (PMID 31139236, 2019). "In the present study, we demonstrate that brain insulin sensitivity was present together with normal memory and explorative performance in early HFDm offspring, whereas cerebral insulin resistance occurred together with impairment in memory and explorative behaviour in adults born to HFD mothers." (PMID 31471539, 2019).